SENP1 (SUMO specific peptidase 1)
Diseases named in the same sentence as SENP1 in open-access papers (continued):
Sharing a sentence is not in itself a finding about the gene and the disease.
cancer (continued). "SENP1 expression levels have been demonstrated to be elevated during prostate pathogenesis while those of CYP24A1 are increased in cancers of the prostate, colon, ovary, and lung, a number of which are known to be insensitive to the growth-regulatory effects of vitamin D." (PMID 24586832, 2014). "Furthermore, SENP1 has also been revealed to be involved in the development and progression of several types of cancer." (PMID 24137315, 2013). "SENP1 has been shown to be overexpressed in several types of cancer." (PMID 24137315, 2013). "Therefore, inhibiting SENP1 activity could be a new strategy for defeating cancer cells, including those resistant to standard treatments." (PMID 41303693, 2025). "Furthermore, the research progress of SENP1 inhibitors for cancer treatment is introduced." (PMID 38389923, 2024). "Furthermore, the present molecular docking studies could contribute to further development and understanding of SENP1 inhibitors for the prevention of cancer." (PMID 37502217, 2023). "Then we suggest that SENP1 could affect cancer prognosis by increasing immune infiltration." (PMID 34276383, 2021). "Therefore, targeting SENP1 has been regarded as a useful approach for cancer therapy." (PMID 33795649, 2021). "However, while SENP1-specific inhibitors have been designed, whether SENP1 is a potential drug target for cancer treatment remains unclear." (PMID 24137315, 2013). "In this study, we demonstrated for the first time that SENP1 is overexpressed in HBV-related HCC and is correlated with poor OS, poor DFS and extrahepatic metastasis, a critical feature of malignant tumors that considerably affects patient prognosis." (PMID 41438340, 2026). "In this study, we show that SUMO conjugation or deconjugation specifically mediated by SENP-1 and SENP-2 proteases represents a novel regulatory mechanism of GRHL2-dependent transcriptional activity in cancer cells." (PMID 40889682, 2025). "SENP1 is one member of the SENP family and modulates the biological characteristics of certain cancers." (PMID 38954215, 2025). "Therefore, the development of SENP1 inhibitors might bring new hope for cancer treatment." (PMID 38389923, 2024). "Mechanistically, miR-145 likely induces apoptosis by targeting SUMO-specific peptidase 1 (SENP1)-mediated hexokinase (HK2) SUMOylation and glycolysis pathways and, in turn, sensitizing the cancer cells to CPT." (PMID 39215325, 2024). "Recently, it has been published that the E3 ubiquitin ligase SMURF2 is lowly expressed in CRC, and when overexpressed it targets YY1 for degradation, which results in inhibition of the SENP1/MYC axis and thereby in cancer prevention." (PMID 35887358, 2022). "By detecting mRNA levels in several TNBC cancer cells (BT549, HCC143, HCC1937, MDA-MB-231), we found that SENP1 mRNA level is highest in MDA-MB-231cells." (PMID 35342335, 2022). "We also checked expression of EMT markers, such as E-Cadherin, Krt12, Vimentin, Survivin, Slug, ZEB1 and ZEB2, in the TNBC cancer cells, and found that expression of ZEB1 was positively correlated with expression of SENP1." (PMID 35342335, 2022). "The positive dependency of SENP1 with lymph node metastasis and TNM Classification of Malignant Tumors (TNM) stage was exhibited by clinical data." (PMID 34276383, 2021). "Given that SENP1 positively regulates MYC levels and activity, SENP1 is an interesting cancer therapeutic target." (PMID 34178666, 2021). "Among the six SENPs (SENP1~3 and SENP5~7), SENP1 is widely located in cell nucleus and plays an essential role in various kinds of human cancers." (PMID 34035184, 2021). "CLDN6 has a potential role in the diagnosis and prognosis of cancers involving deregulated HIF-1α, and subsequently HIF-1α/SENP1-blocked therapies." (PMID 32093760, 2020).
cancer (continued). "In hypoxic conditions, the levels of SUMOylation proteins sharply increase in cancer cells, including SUMO-1, the SUMO E3 ligase PIAS4, the SUMO enhancer RSUME, and SENP1." (PMID 33273928, 2020). "In order to investigate the relationship between SENP1 and HCC, the expression levels of SENP1 in HCC tissues and para-carcinoma tissues were detected by Western blot analysis and immunohistochemistry (IHC)." (PMID 31969492, 2020). "For example, the prognostic impact of SOX9, SENP1 and mTOR was limited to ERG positive cancers while FOXA1, MTCO2 and FOXP2 were only prognostic in ERG negative cancers." (PMID 31606028, 2019). "However, in the same scenario, directly targeting SENP1 could prove as better anti-cancer therapy." (PMID 27852060, 2017). "Subset analyses revealed that the prognostic impact of SENP1 expression was solely driven by the subgroup of ERG positive, PTEN undeleted cancers." (PMID 26202067, 2015). "In addition, a new mechanism for inhibition of HCC growth by LA-CMGL was demonstrated: specifically, miR-145 sensitizes cancer cells to CPT and promotes apoptosis by targeting the SENP1-mediated HK2 SUMOylation and glycolysis pathways." (PMID 39215325, 2024). "Mechanistically, miR-145 may sensitize cancer cells to CPT and promote apoptosis by targeting SENP1-mediated HK2 SUMOylation and glycolysis pathways." (PMID 39215325, 2024). "It is conceivable that by inhibiting MYC deSUMOylation, these SENP1 inhibitors could indirectly suppress MYC deubiquitination, thereby destabilizing MYC and exhibiting anti-proliferative effect in cancer cells." (PMID 34178666, 2021). "In earlier studies we had described several molecular features that were either prognostic in ERG positive (for example, SOX9, and SENP1 or in ERG negative cancers (for example, GGH and NBS1) but not in both groups." (PMID 31043167, 2019). "Next, we postulated that absence of carcinoma in the SENP1-Tg mice was due primarily to the elevated PTEN levels." (PMID 27852060, 2017). "Elevated SENP1 expression levels were strongly linked to deletions of PTEN both in ERG positive and ERG negative cancers (p < 0.0001 each)." (PMID 26202067, 2015). "SENP1 had no prognostic relevance in cancers harboring PTEN deletions, neither in ERG positive (p = 0.7745), nor in ERG negative cancers (p = 0.7267)." (PMID 26202067, 2015). "Since there was no significant prognostic impact of the level of positive SENP1 staining (data not shown), all cancers with weak, moderate, and strong SENP1 staining were combined into one group (“positive”) for follow-up analysis." (PMID 26202067, 2015). "By not altering androgen levels, this SENP1-targeting agent would not prompt the development of androgen-dependent cancer cells." (PMID 24970135, 2012). "However, engineered mice with selective expression of the SENP1 transgene in the epithelia of the prostate gland (PG) do not develop cancer." (PMID 27852060, 2017). "However, our subgroup analyses demonstrated that the significant impact of SENP1 expression on outcome was entirely driven by the subgroup of ERG positive PTEN non-deleted cancers." (PMID 26202067, 2015). "In drug-resistant cells of colorectal cancer, the aberrantly expressed SENP1 could increase the SUMOyaltion of HIF-α, which leads to the conversion of intracellular signal transduction pathway from Wnt/β-catenin to EGFR/IKKα/β/NF-kB, thus reducing the sensitivity of cancer cells to irinotecan." (PMID 37777749, 2023). "However, in vivo data of synthetic SENP1 inhibitors in cancer models are lacking." (PMID 34503213, 2021). "However, SENP1 was largely unrelated to all other deletions irrespective of whether all cancers or subgroups of ERG positive or ERG negative cancers were analyzed." (PMID 26202067, 2015). "HNK is the third plant product identified as a SENP1 inhibitor, potentially useful for the treatment of cancers, in particular HCC, an essentially incurable inflammation-related cancer for which effective medications are still lacking." (PMID 33534099, 2021).
cancer (continued). "SENP1 largely did not provide independent prognostic information if all tumors or the subgroups of ERG positive and ERG negative cancers were interrogated." (PMID 26202067, 2015). "Detectable SENP1 immunostaining was found in 41 % of ERG positive and in 47 % of PTEN deleted cancers but in only 30 % of ERG negative and 30 % of PTEN non-deleted cancers (p < 0.0001 each)." (PMID 26202067, 2015). "Positive SENP1 immunostaining was seen in 41.7 % (ERG IHC) and 40.9 % (ERG FISH) of ERG positive cancers but in only 28.6 % and 30 % of cancers without ERG staining and ERG rearrangement, respectively (p < 0.0001 each)." (PMID 26202067, 2015). "The complete lack of a difference in clinical outcome between PTEN deleted cancers with and without SENP1 expression argues against a clinically relevant cooperative effect of reduced PTEN function and SENP1 activation." (PMID 26202067, 2015). "The application of multivariate models revealed that SENP1 largely lacked independent prognostic value if all tumors and the classical molecular subgroups of ERG positive and ERG negative cancers were analyzed." (PMID 26202067, 2015).
infection (6 papers, 2016 to 2025). The state of being infected such as from the introduction of a foreign agent such as serum, vaccine, antigenic substance or organism. "Our findings reveal that overexpression of SENP1, particularly under Listeria monocytogenes infection conditions (MOI = 20), effectively suppresses inflammation through modulation of glycolysis." (PMID 40071948, 2025). "Mechanistically, during Listeria monocytogenes infection, SENP1 accumulates in the mitochondria, facilitating the de-SUMOylation and activation of sirtuin 3 (SIRT3)." (PMID 40071948, 2025). "No significant change in ROS generation was observed upon knockdown of SENP1 at 30 and 60 min post-infection." (PMID 35734580, 2022). "Our data revealed that infection of L. donovani to the host macrophages leads to upregulation of SUMOylation pathway genes and downregulation of a deSUMOylating gene, SENP1." (PMID 35734580, 2022). "Infection of PMA-differentiated THP-1 macrophages with L. donovani promastigotes significantly upregulated the expression levels of SUMO-1, SUMO-2/3, UBA2, and UBC9 by ≥2-fold, while a significant downregulation of SENP1 was observed at 48 h post-infection at the transcript level." (PMID 35734580, 2022). "Moreover, SENP1 over-expression reduced SMAD4 protein expression at 48 h after infection." (PMID 28417919, 2017). "Pf. sentrin specific protease 1 (SENP1), a SUMO protease, is upregulated by 5.36 ± 2.06 fold on day 3 post-infection of hepatocytes." (PMID 27911910, 2016). "Pf. sentrin specific protease 1 (SENP1), the thiol peptidase required for deSUMOylation and activation of SUMO precursors (SUMO is a small ubiquitin-related modifier) prior to conjugation, is upregulated by 5.36 ± 2.06 on day 3 post-infection by γ-irradiation." (PMID 27911910, 2016). "First data in a proteome analysis from S. aureus infected macrophage-like cell line THP1 showed a decrease in the abundance of the analyzed proteins USP7, USP48, UCHL3, OTUD7B, and SENP1 (data not shown) which might indicate an intracellular role of Spls during infection." (PMID 39985644, 2025).
cardiovascular diseases (4 papers, 2017 to 2023). "Data from clinical research and our previous study have suggested the potential involvement of SENP1, the major protease of post-translational SUMOylation, in cardiovascular disorders." (PMID 28569748, 2017).
prostate (3 papers, 2012 to 2025). "In both folic acid- and IRI induced-AKI models, increased SUMO1 conjugation to Sirt3 was observed, and SENP1-mediated deSUMOylation of Sirt3 alleviated kidney injury." (PMID 41350286, 2025). "Consistently, SENP1 transgenic mice exhibit an induction of HIF1α with the initial onset of PIN (or low-grade PIN) at 4 months of age, suggesting that SENP1 regulation of HIF1α occurs early in prostate pathogenesis." (PMID 24970135, 2012).
neurological diseases (2 papers, 2023 to 2025). "Pure mutations in the SENP1 gene are associated with severe neurological disorders, and SENP1 plays a key role in de-SUMOylation." (PMID 36768153, 2023). "Combined, we propose that the function of SENP1 in the brain may also depend on the cell type, and that strategies targeting SENP1 for neurological diseases should be carefully evaluated to minimize potential side effects." (PMID 41272902, 2025).
cardiac disease (1 paper, 2025). "Collectively, the findings of this study provide new evidence of the interaction with SENP1 promoting LLPS in cells, especially in cardiac disease, solving a puzzle regarding the regulation mechanism of MEF2C stability." (PMID 40341856, 2025). "By combining our present findings on SENP1 and MEF2C deSUMOylation in protecting against ICM, it is highly likely that the modulation of the SUMO system for a selective transcription factor within cardiomyocytes is critical in the pathogenesis of cardiac disease." (PMID 40341856, 2025).
kidney diseases (1 paper, 2014). "In summary, our study is the first to reveal the beneficial effects of SENP1 on the treatment of kidney diseases." (PMID 25411797, 2014).
SENP1 also shares sentences with these, for which no sentence is quoted: Cerebral ischemia (3 papers); gastric cancer (2); acute kidney injury (1); autism spectrum disorder (1); brain disorder (1); breast tumors (1); Burkitt lymphoma (1); chronic obstructive pulmonary disease (1); gastric tumor (1); hepatic echinococcosis (1); idiopathic pulmonary fibrosis (1); ischemic heart disease (1); Leigh syndrome (1); lung squamous cell carcinoma (1); lymphoid neoplasm (1); metastasis (1); Myocardial fibrosis (1); Obesity (1); ovarian failure (1); pancreatic adenocarcinoma (1); Parkinson disease (1); polycythemia (1); prostate tumor (1); renal carcinoma (1); Sepsis (1); skin melanoma (1); small cell lung carcinoma (1); thymoma (1); uterine corpus endometrial carcinoma (1).